NPC1 (NPC intracellular cholesterol transporter 1)
Diseases named in the same sentence as NPC1 in open-access papers (continued):
Sharing a sentence is not in itself a finding about the gene and the disease.
Niemann-Pick disease type C (continued). "Niemann−Pick disease type C (NPC) is a rare neurodegenerative disorder caused by a recessive mutation in the NPC1 or NPC2 gene, in which patients exhibit lysosomal accumulation of unesterified cholesterol and glycolipids." (PMID 34377675, 2021). "Niemann–Pick disease type C (NPC) is a recessive hereditary disease caused by mutation of the NPC1 or NPC2 gene." (PMID 33466390, 2021). "Niemann-Pick type C disease (NPCD) is a lysosomal storage disorder caused by mutations in the NPC1 gene." (PMID 34440927, 2021). "Niemann-Pick type C disease is a rare neurodegenerative disorder mainly caused by mutations in NPC1, resulting in abnormal late endosomal/lysosomal lipid storage." (PMID 33627648, 2021). "Niemann–Pick disease type C (NPC) is the rare neurodegenerative disease caused by mutations of NPC1 (~95%) and NPC2 (~5%) that lead to the progressive neurodegeneration of the central nervous system." (PMID 33311479, 2020). "While homozygous pathogenic mutations in the NPC1 gene cause Niemann-Pick type C1 disease, heterozygous mutations cause highly-penetrant obesity." (PMID 33139814, 2020). "Niemann-Pick disease type C (NPC) is an autosomal recessive disorder caused by mutations of NPC1 or NPC2, which encode the proteins that are responsible for intracellular cholesterol trafficking." (PMID 32898135, 2020). "Niemann–Pick disease, type C1 (NPC1, MIM #257220) is a rare neurodegenerative disease caused by reduced function of NPC1." (PMID 32731618, 2020). "Niemann–Pick disease type C (NPC) is a recessive genetic lysosomal storage disease caused by mutations in the NPC1 or NPC2 proteins, important transporters of cholesterol from endosomes and lysosomes." (PMID 32611604, 2020). "Niemann-Pick disease, type C (NPC) is a neurodegenerative lysosomal storage disorder caused by mutations in the NPC1 or NPC2." (PMID 33311479, 2020). "Human fibroblasts that carry mutations in Niemann-Pick C1 (NPC1), whose mutations are responsible for the Niemann-Pick type C disease, display high levels of SFAs and a reduced membrane fluidity." (PMID 31408455, 2019). "The NPC1 knock-out mouse (NPC1 KO) and a knock-in of the most common NPC1 patient mutation I1061T are established models of Niemann-Pick type C disease." (PMID 30775969, 2019). "Niemann Pick Type-C disease (NPC) is an inherited lysosomal storage disease (LSD) caused by pathogenic variants in the Npc1 or Npc2 genes that lead to the accumulation of cholesterol and lipids in lysosomes." (PMID 31605022, 2019). "Mutations of either NPC intracellular cholesterol transporter 1 or 2 (Npc1 or Npc2) cause the Niemann-Pick Type C disease (NPC), which is a rare recessive neurological disorder." (PMID 30866987, 2019). "The rare lysosomal storage disorder Niemann-Pick disease type C1 (NPC1) arises from mutation of NPC1, which encodes a lysosomal transmembrane protein essential for normal transport and trafficking of cholesterol and sphingolipids." (PMID 31861571, 2019). "Niemann-Pick type C disease (NP-C) is a neurovisceral autosomal recessive lysosomal storage disease caused by mutations in the NPC1 gene." (PMID 31700700, 2019). "Niemann-Pick type C disease (NPC) is a genetically determined neurodegenerative metabolic disease resulting from the mutations in the NPC1 or NPC2 genes." (PMID 31197681, 2019). "Niemann-Pick type C disease (NP-C) is a fatal neurodegenerative disorder caused by a deficiency in the function of the NPC1 gene." (PMID 31700700, 2019). "Niemann-Pick disease type C (NPC) is caused by mutations of the NPC1 and NPC2 genes that result in impaired cellular processing and transport of low-density lipoprotein (LDL)-cholesterol." (PMID 30650529, 2019). "Niemann-Pick disease type C (NP-C) is a neurodegenerative lysosomal lipid storage disease caused by autosomal recessive mutations in the NPC1 or NPC2 genes." (PMID 30285904, 2018).
Niemann-Pick disease type C (continued). "Niemann-Pick type C1 disease is most commonly caused by the allele NPC1 I1061T, which is misfolded in the ER and rapidly degraded by the ubiquitin proteasome system." (PMID 30202070, 2018). "Niemann–Pick type C disease is a fatal, progressive neurodegenerative disorder caused by loss-of-function mutations in NPC1, a multipass transmembrane glycoprotein essential for intracellular lipid trafficking." (PMID 30202070, 2018). "Niemann-Pick disease type C (NP-C) is a rare, progressive neurodegenerative disease caused by mutations in the NPC1 or the NPC2 gene." (PMID 29871644, 2018). "Niemann Pick disease type C (NP-C) is a neurovisceral lysosomal storage disorder caused by autosomal recessive mutations in the NPC1 (≥95% of cases) or the NPC2 gene and is characterized by impaired trafficking of cholesterol and sphingolipids." (PMID 30285904, 2018). "Niemann-Pick disease type C (NP-C) is a rare, progressive neurodegenerative disease caused by mutations in the NPC1 or the NPC2 gene, which lead to impaired cholesterol metabolism." (PMID 29871644, 2018). "We validated our approach by comparing the biomolecular compositions of lysosomes and plasma membranes isolated from wild-type and Niemann-Pick disease type C1 (NPC1) deficient cells." (PMID 28134274, 2017). "Niemann-Pick disease Type C1 (NPC1) is a rare progressive neurodegenerative disorder caused by mutations in the NPC1 gene." (PMID 28841900, 2017). "Niemann-Pick disease type C (NP-C) is a rare, autosomal recessive neurodegenerative disease caused by mutations in either the NPC1 or NPC2 genes." (PMID 28222799, 2017). "Niemann–Pick disease, type C1 (Npc1), is an atypical lysosomal storage disorder caused by autosomal recessive inheritance of mutations in Npc1 gene." (PMID 27860245, 2017). "Niemann-Pick disease type C (NPC) is a rare neurovisceral disease caused mainly by mutations in the NPC1 gene." (PMID 28167839, 2017). "The lysosomal storage diseases Niemann‐Pick disease type C (NPC) is caused by mutations predominantly in the lysosomal integral membrane protein NPC1 and clinically presents as a progressive neurodegenerative disorder." (PMID 25946402, 2016). "In humans, the loss of the protein encoded by NPC1 causes a rare but very severe disease called Niemann-Pick type C disease." (PMID 26698106, 2015). "Niemann–Pick type C1 disease (NPC1) is a rare progressive neurodegenerative disease caused by mutations in the NPC1 gene, leading to an impaired lipid transport and an accumulation of cholesterol and gangliosides in the late endosomes and lysosomes." (PMID 26392920, 2015). "Niemann–Pick type C1 disease (NPC1) is a neurodegenerative disorder caused by mutations in the NPC1 gene." (PMID 26392920, 2015). "Mutations in NPC1 cause Niemann-Pick disease type C, in which progressive neurological symptoms, including dementia, dystonia, and ataxia, are hallmarks." (PMID 26275289, 2015). "Niemann pick type C disease is a rare neurovisceral lysosomal storage disorder caused by mutations in either NPC1 or NPC2 genes." (PMID 25396745, 2014). "Niemann Pick disease type C (NP-C) is a rare autosomal recessive disorder that results from mutations in either the NPC1 or the NPC2 gene." (PMID 25145893, 2014). "Niemann-Pick disease type C (NP-C) is caused by mutations in either the NPC1 or the NPC2 gene, it is a rare neurovisceral lysosomal storage disorder (LSD) which leads to progressive neuropsychiatric deterioration and in the majority of cases, premature death." (PMID 25479233, 2014). "Niemann-Pick disease type C (NPC) is caused by defects in cholesterol efflux from lysosomes due to mutations of genes coding for NPC1 and NPC2 proteins." (PMID 24775609, 2014). "Mutations in the human NPC1 gene cause Niemann-Pick type C disease (NPC), a fatal childhood-onset neurodegenerative disorder." (PMID 23593041, 2013).
Niemann-Pick disease type C (continued). "Loss of function mutations in the human NPC1 gene cause Niemann-Pick type C disease, a childhood-onset neurodegenerative disorder in which intracellular lipid accumulation, abnormally swollen axons, and neuron loss underlie the occurrence of early death." (PMID 23593041, 2013). "Niemann-Pick type C1 disease (NPC1) is a rare progressive neurodegenerative disorder caused by mutations in the NPC1 gene." (PMID 24044630, 2013). "Niemann–Pick disease type C (NP-C) is a rare, autosomal-recessive, progressive neurological disease caused by mutations in either the NPC1 gene (in 95% of cases) or the NPC2 gene." (PMID 23773996, 2013). "Mutations of Npc1 are responsible for most cases of Niemann-Pick disease type C, which is associated with abnormal accumulation of cholesterol and other lipids within cells." (PMID 22253740, 2012). "Niemann Pick disease type C1 is a neurodegenerative disease caused by mutations in the NPC1 gene, which result in accumulation of unesterified cholesterol and glycosphingolipids in the endosomal-lysosomal system as well as limiting membranes." (PMID 22163015, 2011). "However, Niemann-Pick disease type C, a disease caused by mutations in the NPC1 and NPC2 genes, is accompanied by psychiatric symptoms – mainly psychotic, mood-related, and impulse control-related." (PMID 41044382, 2026). "Mutations in NPC1 cause Niemann-Pick type C disease, a rare lipid storage disorder." (PMID 39762312, 2025). "Niemann–Pick disease type C (NPC) is another LSD associated with significant CNS involvement caused by mutations in the NPC1 or NPC2 gene, leading to impaired intracellular trafficking and the accumulation of cholesterol and glycosphingolipids within lysosomes." (PMID 39525762, 2024). "Niemann–Pick disease type C (NPC) is a fatal neurodegenerative condition caused by genetic mutations of the NPC1 or NPC2 genes that encode the NPC1 and NPC2 proteins, respectively, which are believed to be responsible for cholesterol efflux from late-endosomes/lysosomes." (PMID 38254990, 2024). "Collectively, these results suggested a putative A2AR-mediated regulation of NPC1 protein function in macrophages, potentially relevant for the Niemann–Pick type C disease when mutations in NPC1 protein result in the accumulation of cholesterol and other lipids in lysosomes." (PMID 37367064, 2023). "Mutations in NPC1 have been implicated in causing ∼95% of human Niemann–Pick type C disease cases." (PMID 36861884, 2023). "NPC1 mediates intracellular trafficking of cholesterol and glycolipids, and mutations in NPC1 are responsible for 95% of cases of Niemann-Pick disease type C, a lysosomal storage disease characterized by intracellular accumulation of cholesterol and glycosphingolipids in various tissues." (PMID 37792698, 2023). "The intracellular cholesterol transporter NPC1 functions in late endosomes and lysosomes to efflux unesterified cholesterol, and its deficiency causes Niemann–Pick disease Type C, an autosomal recessive lysosomal disorder characterized by progressive neurodegeneration and early death." (PMID 37407594, 2023). "NPC1 deficiency leads to the early degeneration of neurons in Niemann-Pick Type C disease." (PMID 38033125, 2023). "In humans, mutations in either NPC1 or NPC2 lead to the development of Niemann–Pick disease type C (NPC disease), a lysosomal storage disorder with a broad spectrum of visceral and neurological symptoms resulting from cellular accumulation of cholesterol and glycolipids." (PMID 34050187, 2021). "Since the clinical syndrome fitted that well, genetic testing was performed and the diagnosis of Niemann–Pick disease type C1 was very likely due to a compound heterozygous mutation of the NPC1 gene, consisting of a frameshift (p.V1023Sfs*15) and a missense mutation (p.G992R), respectively." (PMID 34830064, 2021).
Niemann-Pick disease type C (continued). "Mouse colonies of two other monogenetic autosomal recessive disorders, sickle cell anemia (carrying a point mutation in the β -globin gene; and Niemann-Pick Type C disease (carrying a point mutation in Npc1 gene) yielded homozygous mutant progeny at rates between 21–22%." (PMID 33524012, 2021). "NPC1 (Niemann-Pick C1), one of the components of cholesterol exporting system from the lysosome, would result in the accumulation of cholesterol and glycolipids, called Niemann-Pick disease type C (NPC), if mutated." (PMID 32964017, 2020). "Little is known about the effects of NPC1 deficiency in brain development and whether these effects contribute to neurodegeneration in Niemann–Pick disease type C (NPC)." (PMID 32611604, 2020). "However, enhanced anxiety is observed in the patients with Niemann-Pick diseases, type C, which is characterized by sphingolipid accumulation in biological tissues and organs due to the mutations in the NPC1 or NPC2 genes." (PMID 31333574, 2019). "Moreover, Niemann-Pick disease type C is a neurodegenerative disorder with mutation in the NPC1 or NPC2 (Niemann-Pick disease, type C1 or C2) genes, which encode proteins involved in cholesterol transport." (PMID 31357643, 2019). "Further, progressive neurological symptoms prompted additional genetic analyses for possible Niemann–Pick disease type C, from which an as-yet unreported combination of known NPC1 gene mutations was identified, and a final diagnosis of Niemann–Pick disease type C was established." (PMID 27250337, 2016). "Niemann–Pick disease type C (NP-C) is a rare neurodegenerative disease caused by autosomal recessive mutations in either the NPC1 gene (in 95 % of cases) or the NPC2 gene, resulting in impaired intracellular lipid trafficking and accumulation of glycolipids in various tissues including the brain." (PMID 27599728, 2016). "Over time he developed characteristic, progressive vertical ophthalmoplegia, ataxic gait, and cerebellar syndrome; at age 10 he was diagnosed as having Niemann–Pick disease type C based on filipin staining and genetic analysis (heterozygous I1061T/R934X NPC1 mutations)." (PMID 27599728, 2016). "Similarly, Niemann-Pick disease type C (NPC) is caused by defects in cholesterol efflux from lysosomes due to mutations in genes coding for NPC1 and NPC2 proteins." (PMID 25949827, 2015). "Niemann–Pick disease type C (NP-C) is a rare inherited lysosomal storage disorder caused by autosomal recessive mutations in either the NPC1 gene (in 95% of cases) or the NPC2 gene, and is characterized by progressive neurological deterioration and premature death." (PMID 23773996, 2013). "Niemann-Pick disease type C homozygous for NPC1 mutation p.S940L [c." (PMID 23146215, 2012). "The dynamics of late endosome-specific lipids is profoundly altered in Niemann-Pick type C disease, a neurodegenerative disorder in which a mutation in the NPC1 protein, a regulator of vesicular cholesterol transport, causes massive accumulation of cholesterol and LBPA in late endosomes." (PMID 19956591, 2009). "Niemann-Pick disease type C (NP-C) is a devastating, neurovisceral lysosomal storage disorder which is characterised by variable manifestation of visceral signs, progressive neuropsychiatric deterioration and premature death, caused by mutations in the NPC1 and NPC2 genes." (PMID 25479233, 2014). "Npc1 encodes a transmembrane protein critical for mobilizing exogenously derived cholesterol from late endosomes and lysosomes, and is mutated in patients with Niemann-Pick type C disease, a degenerative disorder caused by impaired intracellular lipid trafficking." (PMID 23593041, 2013). "Niemann-Pick disease, type C (NPC), is an inherited fatal lysosomal storage disorder caused by a mutation in the NPC1 or NPC2 genes and characterized by impaired lysosomal cholesterol export." (PMID 41811855, 2026).
Niemann-Pick disease type C (continued). "Diseases related to NPC1 include Niemann-Pick disease type C1, a rare autosomal recessive genetic disorder." (PMID 39762312, 2025). "Niemann–Pick Disease Type C (NPC) is a rare neurodegenerative disorder caused by mutations in the genes NPC1 (Chr.18q11.2) and/or NPC2 (Chr.14q24.3), with NPC1 mutations accounting for 95% of cases." (PMID 40243519, 2025). "Despite over a century of research on Niemann-Pick disease type C and extensive structural studies on NPC1, its function in cancer has been relatively unexplored." (PMID 39762312, 2025). "Niemann–Pick type C disease (NPC) is a neurodegenerative disorder classified into types C1 and C2 depending on the respective human gene (NPC1 or NPC2) that is mutated." (PMID 41511290, 2025). "Knockdown of σ2R/TMEM97 upregulates NPC1 expression, reduces cholesterol accumulation, and improves cholesterol trafficking in a cell model of Niemann–Pick type C1 disease." (PMID 41008535, 2025). "The activation of ER stress response is additional evidence that C10 is mechanistically distinct from NPC1 inhibitor as mouse and cellular models of Niemann-Pick type C disease are unable to activate the ER stress response." (PMID 38697978, 2024). "Niemann-Pick disease type C1 (NPC1, MIM 257220) is a heritable lysosomal storage disease characterized by a progressive neurological degeneration that causes disability and premature death." (PMID 39081805, 2024). "Niemann-Pick disease type C (NPC) is an autosomal recessive, progressive disorder resulting from variants in NPC1 or NPC2 that leads to the accumulation of cholesterol and other lipids in late endosomes and lysosomes." (PMID 39061081, 2024). "Mutations in NPC1 and NPC2 genes are the cause of Niemann-Pick disease, type C that leads to lysosomal accumulation of cholesterol." (PMID 39106189, 2024). "We report human iNeurons and mice expressing human I1061T NPC1, and we demonstrate their utility in identifying proteostatic therapies for Niemann-Pick type C disease." (PMID 39207850, 2024). "Niemann–Pick disease type C (NPC) is a rare and fatal neurological disorder caused by mutations in Npc1 or Npc2, with Npc1 accounting for 95% of cases." (PMID 39202426, 2024). "Pathologically, mutations of the NPC1 and NPC2 genes induce the fetal inherited disorder Niemann-Pick disease type C (NPDC), wherein cholesterol aberrantly accumulates in lysosomes." (PMID 38136141, 2023). "The mutation of NPC1 and NPC2 genes induces Niemann-Pick disease type C (NPDC), which is a hereditary disease and causes progressive neurodegeneration, developmental disability, hypotonia, and ataxia." (PMID 38136141, 2023). "To clarify which stage of lipid uptake was affected by vimentin, we used U18666A, a specific inhibitor for NPC-1 (Niemann-Pick disease, type C1)." (PMID 35656400, 2022). "Niemann–Pick disease type C1 (NPC1) exhibits marked variability in disease phenotype and onset, the extent to which is attributed to different NPC1 mutations that exhibit a more mild or more severe phenotype." (PMID 35563467, 2022). "Niemann-Pick disease type C (NPC) is a rare, autosomal recessive, lysosomal storage disease, resulting from mutations in the cholesterol trafficking proteins NPC1 or NPC2, which is characterized by progressive neurodegeneration and hepatic dysfunction." (PMID 36636588, 2022). "Disruption of NPC1 results in cholesterol accumulation in late endosomes and leads to Niemann-Pick disease type C, an autosomal-recessive neurodegenerative disorder." (PMID 35263388, 2022). "A dysfunction of NPC1 activity results in Niemann–Pick type C disease partly because of a disruption of membrane raft formation, which also works as an obstacle to viral entry into cells." (PMID 34850606, 2022). "NPC1 and Rab9, with a 98% correlation, are important players in cholesterol metabolism and Niemann Pick Disease Type C." (PMID 35255958, 2022).